GNB2 (G protein subunit beta 2)
Description:
Guanine nucleotide-binding proteins (G proteins) are involved as a modulator or transducer in various transmembrane signaling systems. The beta and gamma chains are required for the GTPase activity, for replacement of GDP by GTP, and for G protein-effector interaction.
Synonyms: HG2C1; NEDHYDF; SSS4; SSS4; NEDHYDF
Tractability: Small molecule: a structure with a bound ligand is known. Antibody: UniProt places it where antibodies can reach, with high confidence; its Gene Ontology location is reachable by antibodies, with high confidence; the Human Protein Atlas places it where antibodies can reach. PROTAC: ubiquitination databases record sites on it; its protein half-life has been measured.
Gene: Protein-coding gene on chromosome 7 (100,673,567 to 100,679,174, forward strand). Ensembl gene ENSG00000172354.
Subcellular location: Cytoplasm, perinuclear region; Cell membrane
Subcellular location (Human Protein Atlas): Plasma membrane
Pathways (Reactome):
Signal Transduction: Ca2+ pathway; Extra-nuclear estrogen signaling; G alpha (12/13) signalling events; G alpha (i) signalling events; G alpha (q) signalling events; G alpha (s) signalling events; G alpha (z) signalling events; G beta:gamma signalling through BTK; G beta:gamma signalling through CDC42; G beta:gamma signalling through PI3Kgamma; G beta:gamma signalling through PLC beta; G-protein activation; GPER1 signaling; Glucagon-type ligand receptors
Hemostasis: ADP signalling through P2Y purinoceptor 1; ADP signalling through P2Y purinoceptor 12; Prostacyclin signalling through prostacyclin receptor; Thrombin signalling through proteinase activated receptors (PARs); Thromboxane signalling through TP receptor
Metabolism: Adrenaline,noradrenaline inhibits insulin secretion; Glucagon signaling in metabolic regulation; Glucagon-like Peptide-1 (GLP1) regulates insulin secretion
Neuronal System: Activation of G protein gated Potassium channels; Inhibition of voltage gated Ca2+ channels via Gbeta/gamma subunits; Presynaptic function of Kainate receptors
Cellular responses to stimuli: High laminar flow shear stress activates signaling by PIEZO1 and PECAM1:CDH5:KDR in endothelial cells
Disease: ADORA2B mediated anti-inflammatory cytokines production
Metabolism of proteins: Cooperation of PDCL (PhLP1) and TRiC/CCT in G-protein beta folding
Transport of small molecules: Vasopressin regulates renal water homeostasis via Aquaporins
Gene Ontology:
Molecular function: GTPase binding; protein binding; protein-containing complex binding; GTPase activity; signaling receptor complex adaptor activity
Biological process: regulation of potassium ion transmembrane transport; G protein-coupled receptor signaling pathway; signal transduction
Cellular component: extracellular exosome; extracellular region; focal adhesion; lysosomal membrane; membrane; perinuclear region of cytoplasm; plasma membrane; vesicle; cytosol; synapse
Genetic constraint (gnomAD): Loss-of-function variants: 7 observed, 35.35 expected, observed/expected ratio (o/e) 0.2, 90% interval 0.11 to 0.37. The synonymous counts are far from expectation, so gnomAD's model fits this gene poorly and the ratio says little. Missense variants: 277 observed, 457.59 expected, observed/expected ratio (o/e) 0.61, 90% interval 0.55 to 0.67. Synonymous variants: 238 observed, 188.42 expected, observed/expected ratio (o/e) 1.26, 90% interval 1.14 to 1.41.
Homologues: Orthologues: chimpanzee GNB2 (100% identical), dog GNB2 (100% identical), guinea pig GNB2 (100% identical), macaque GNB2 (100% identical), mouse Gnb2 (100% identical), pig GNB2 (100% identical), rat Gnb2 (100% identical), chimpanzee GNB2 (96% identical), zebrafish gnb2 (95% identical), Caenorhabditis elegans gpb-1 (85% identical), rabbit GNB2 (84% identical), Drosophila melanogaster Gbeta13F (81% identical). Paralogues in human: GNB1 (90% identical), GNB4 (90% identical), GNB3 (81% identical), GNB5 (52% identical).
Diseases named in the same sentence as GNB2 in open-access papers:
GNB2 is named in the same sentence as 38 diseases in open-access papers, as found by Europe PMC text mining. Sharing a sentence is not in itself a finding about the gene and the disease. The quoted sentences say what the papers report.
breast carcinoma (4 papers, 2019 to 2026). "In the ieu-a-1126 cohort, genes with causal relationships to breast cancer included GNB2, HADH, OAS2, OCIAD2, P4HA2, and PAFAH1B3." (PMID 41424847, 2026). "This signal integration function of GNB2 is supported by prior studies in breast cancer, where it was shown to be a direct target of miR-142-3p; GNB2 knockdown activated AKT/mTOR signaling, altered autophagic flux, and modulated chemotherapeutic sensitivity." (PMID 41550840, 2026). "miR‐142‐3p was found to alter paclitaxel resistance by targeting recombinant G protein beta 2 (GNB2), regulate migration and autophagy energy of breast cancer cells, and further reveal that knockdown of GNB2 expression can activate AKT–mTOR pathway." (PMID 38263865, 2024). "Network analysis on the cancer genome atlas (TCGA) breast cancer dataset revealed interaction between CXCL12 and CXCR7 (ACKR3), and a number of G-protein family members (GNG5, GNB4, GNB2, GNG12, GNG7, GNGT1, and GNAI3)." (PMID 30993013, 2019).
colorectal cancer (3 papers, 2021 to 2026). A primary or metastatic malignant neoplasm that affects the colon or rectum. "Together, these findings indicate that the Snhg5/GNB2 axis promotes EMT and activates the Wnt/β-catenin pathway, thereby contributing to the metastatic phenotype of colorectal cancer cells." (PMID 41550840, 2026). "We found that there were intensive protein-protein interaction pairs, and 3 potential hub genes (POLR2B, GNB2, and GNG2) were identified, which suggested that universal recurrence associated genes may cooperate together to have an impact on the recurrence of stage II colorectal cancer patients." (PMID 33628243, 2021).
glioma (3 papers, 2021). A benign or malignant brain and spinal cord tumor that arises from glial cells (astrocytes, oligodendrocytes, ependymal cells). "GNB2 subgroup predicted poor survival in patients with gliomas, especially in patients with LGG with mutation IDH and non-codeleted 1p19q." (PMID 34222011, 2021). "GNB2 subgroup also exhibited worse OS in patients with glioma with mutated IDH, wild type IDH, and non-codeleted 1p19q." (PMID 34222011, 2021). "High M2 macrophages infiltration was associated with poor prognosis in patients with glioma, which partly explained the short OS in GNB2 patients." (PMID 34222011, 2021). "Additionally, GNB2 subgroup predicted poor survival in patients with gliomas, especially in patients with LGG with mutation IDH and non-codeleted 1p19q." (PMID 34222011, 2021). "When characterizing the abundances of different immune cell types with CIBERSORTx, we found that the infiltration levels of M0 macrophages and M2 macrophages increased significantly in glioma samples of GNB2 subgroup in both the CGGA and TCGA datasets." (PMID 34222011, 2021). "Significant correlation was observed between GNB2 subgroup and decreased OS was observed in patients with glioma as well." (PMID 34222011, 2021). "The roles of FZD8, GNG12, GNB2 have not been fully illustrated in gliomas and needs further investigation." (PMID 35116059, 2021). "The characteristics of GNB2 subgroup, including IDH wildtype, 1p19q non-codeletion, high infiltration of M2 macrophages, all predicted poor survival in patients with gliomas." (PMID 34222011, 2021).
leukemia (2 papers, 2019 to 2022). A malignant (clonal) hematologic disorder, involving hematopoietic stem cells and characterized by the presence of primitive or atypical myeloid or lymphoid cells in the bone marrow and the blood. "Mutations and overexpression of GNB2 can cause leukemia, and downregulation of GNB2 expression reduces the cell proliferation potential and confers survival benefits." (PMID 35841000, 2022). "Out of these candidate mutations, clone size of Gnb2 mutation significantly elevated during serial transplantation and this mutation was significantly associated with earlier leukemia onset." (PMID 30209403, 2019). "In this study of MLL/AF9-AML, we showed that a novel activating mutation of Gnb2 were clearly pathogenic in a mouse leukemia model and that high expression of GNB2 may play a significant role in human MLL-AML." (PMID 30209403, 2019). "In fact, according to ChIP sequencing of multiple hematopoietic cell lines, promoter sites of GNB2 were remarkably identified as binding regions of tri-methylated histone H3K4, which serves a major role of oncogenic potential in MLL-associated leukemia." (PMID 30209403, 2019). "Therefore, expression of GNB2, whose activating mutation was acquired during mouse MLL/AF9 leukemia, might be epigenetically regulated by MLL fusion protein." (PMID 30209403, 2019).
malignant melanoma (2 papers, 2022 to 2024). "In particular, retinal density– and FD-lowering alleles at several PoPS-prioritized genes showed associations with higher risk of skin neoplasms, malignant melanoma, and eye cancer (IRF4/DUSP22, SLC45A2); a separate set of loci showed associations with lighter skin color (GNB2, ACTG1)." (PMID 34743558, 2022).
rectal adenocarcinoma (2 papers, 2024 to 2026). "In both hepatocellular carcinoma and rectal adenocarcinoma, elevated GNB2 levels correlated with reduced overall survival." (PMID 41550840, 2026). "GNB2 was upregulated in 23 types of cancer, and its increased expression was associated with a lower overall survival (OS) in liver hepatocellular carcinoma (LIHC) and rectal adenocarcinoma (READ)." (PMID 39336799, 2024).
schizophrenia (2 papers, 2018 to 2022). A major psychotic disorder characterized by abnormalities in the perception or expression of reality. "Previous studies show that GNB2 and its coding proteins are highly expressed in brain tissue, and de novo mutations in GNB2 show effects on synaptic proteins and genes involved in schizophrenia and other neuropsychiatric diseases." (PMID 35386517, 2022). "GNB2 has been found differentially expressed in the anterior cingulate cortex from patients with schizophrenia." (PMID 30255799, 2018).
Sturge-Weber syndrome (2 papers, 2024 to 2025). Sturge-Weber syndrome (SWS) is a rare congenital neurocutaneous disorder characterized by facial capillary malformations and/or cerebral and ocular ipsilateral vascular malformations that result in variable degrees of ocular and neurological anomalies. "Case reports have been published for GNB2, CBL and PIK3CD, describing patients with Sturge-Weber syndrome (GNB2) or lymphatic anomalies (CBL and PIK3CD)." (PMID 38778413, 2024).
chronic sinusitis (1 paper, 2018). "Other G-protein receptors such as IKACH, GNB2 are linked to some other forms of sinusitis but this association between functional annotation mutations in TACR1 and chronic sinusitis is novel." (PMID 29545597, 2018).
colorectal adenocarcinoma (1 paper, 2019). The most common type of colorectal carcinoma. "GNB2 mutations were also identified in several cancers, including diffuse large B-cell lymphoma, colorectal adenocarcinoma, and lung small cell carcinoma." (PMID 30209403, 2019).
developmental delay (1 paper, 2019). "This study highlights that GNB2 variants not only associate to cardiac manifestations, but cause developmental delay too." (PMID 31817184, 2019).
diabetes (1 paper, 2022). "There was a significant upregulated expression of GNB2 gene in patients with diabetes and hypertension (Group I) compared to Group II (AT) (p=0.0467)." (PMID 36523663, 2022). "Several studies have depicted the role of GNB2, and TCF in the pathogenesis of diabetes and hypertension and the variation of expression in tobacco and alcohol users." (PMID 36523663, 2022).
Insulin resistance (1 paper, 2018). Increased resistance towards insulin, that is, diminished effectiveness of insulin in reducing blood glucose levels.
vascular malformation (1 paper, 2024). A non-neoplastic disorder that is the result of defects of vascular morphogenesis. "The remaining four genes (ARAF, CBL, GNB2 and PIK3CD) have been associated with vascular malformations with “limited evidence”." (PMID 38778413, 2024).
cancer (8 papers, 2013 to 2026). A tumor composed of atypical neoplastic, often pleomorphic cells that invade other tissues. "Further, the G family proteins, GNB1 and GNB2 are implicated in cancer proliferation, survival, invasion, metastasis, survival and resistance." (PMID 32350346, 2020). "Mutations of GNB2 may result in targeted kinase inhibitors resistance to numerous types of cancer." (PMID 35116059, 2021). "Recent multi-omics analyses have revealed aberrant overexpression of GNB2 across a range of human cancers." (PMID 41550840, 2026). "GNB2 was involved in cancer initiation and progression by activating AKT/mTOR pathway, MAPK pathway, and Hippo signaling pathway." (PMID 35116059, 2021). "GNB2 may activate the canonical G protein signaling and involved in cancer initiation and progression." (PMID 35116059, 2021).
tumor (6 papers, 2019 to 2026). "Both mutation and overexpression of GNB2 caused leukemogenesis, let alone downregulation of GNB2 expression reduced proliferative potential of tumor cells." (PMID 34222011, 2021). "To further investigate tumor formation associated with GNB2, we performed in vivo experiments in which Ba/F3 cells with mock, wild-type GNB2, and mutant GNB2 were transplanted subcutaneously to nude mice and intravenously to NOG mice." (PMID 30209403, 2019). "Several molecular markers of GNB2 subgroup were associated with tumor progression." (PMID 34222011, 2021). "GNB2 has been reported to be frequently mutated and upregulated in many hematological neoplasms, and a lower expression of GNB2 could reduce the proliferation potential of tumor cells." (PMID 35096824, 2021). "Quantification showed a significantly higher proportion of GNB2-positive cells in tumor tissues compared with normal controls (p < 0.05)." (PMID 41550840, 2026). "Functionally, SNHG5 promoted cell proliferation, migration, epithelial–mesenchymal transition (EMT), and suppressed apoptosis, while GNB2 overexpression partially rescued the tumor-suppressive phenotypes induced by SNHG5 silencing." (PMID 41550840, 2026). "Consistently, the liver-to-body weight ratio, a surrogate marker of tumor load, was significantly elevated in the GNB2-overexpressing group and reduced upon Snhg5 silencing." (PMID 41550840, 2026). "Functional rescue assays demonstrated that GNB2 mediates SNHG5-induced tumor-promoting effects by activating the PI3K/AKT pathway, a canonical oncogenic axis." (PMID 41550840, 2026). "An analysis of the underlying mechanism identified a total of 21 interacting proteins implicated in tumor formation, and among these, AKT1, CDK4, GNB2, and MAPK8 were confirmed at both gene and protein levels." (PMID 39336799, 2024). "Compared between wild type vs. mutant GNB2 experiments in nude mice, tumor volumes were significantly larger in mutant than in wild type (P < 0.001 on day 14, 21, and 28)." (PMID 30209403, 2019). "Next compared between mock vs. wild-type GNB2 groups, tumor volumes were significantly larger in wild-type experiments than in mock (P < 0.01 on day 35, 42, and 49)." (PMID 30209403, 2019).
hematological neoplasms (2 papers, 2019 to 2021). "Another mutated gene of interest was Gnb2 which was reported to be recurrently mutated in various hematological neoplasms." (PMID 30209403, 2019). "Another mutated gene of interest was Gnb2 in Strain B1 mice which was reported to be recurrently mutated in various human hematological neoplasms." (PMID 30209403, 2019). "Though GNB2 mutations were not identified in human MLL-AML, Gnb2 mutation had a significant impact on poor prognosis in mouse MLL/AF9-AML, increased in clone size during the serial transplantation, and existed in other human hematological neoplasms." (PMID 30209403, 2019).
neurodevelopmental disorder (2 papers, 2022 to 2023). A behavioral and cognitive disorder with onset during the developmental period that involves impaired or aberrant development of intellectual, motor, or social functions. "Polymorphisms or mutations in GNB1, GNB2, and GNB5 genes were reported to be associated with neurodevelopmental disorders." (PMID 36077181, 2022). "In addition, other mutations in GNB2 and GNB5 are observed in patients with neurodevelopmental disorders." (PMID 36648066, 2023).
bacterial infections (1 paper, 2022). "A similar situation is observed in the case of GNB2, which is involved as a modulator or transducer in various transmembrane signaling systems, including inflammasome creation, especially in bacterial infections but not in viral." (PMID 35457192, 2022).
GNB2 also shares sentences with these, for which no sentence is quoted: infection (2 papers); acute myeloid leukemia (1); Alzheimer disease (1); atherosclerosis (1); Crohn disease (1); diffuse large B-cell lymphoma (1); dilated cardiomyopathy (1); escherichia coli infection (1); eye cancer (1); heart disease (1); hemorrhage (1); hepatocellular carcinoma (1); Hypertension (1); ischemic cardiomyopathy (1); lung small cell carcinoma (1); neurological disorder (1); osteosarcoma (1); skin neoplasm (1); Waardenburg syndrome (1).